MIR586 (microRNA 586)
Synonyms: hsa-mir-586; MIRN586
Gene: MicroRNA gene on chromosome 6 (45,197,674 to 45,197,770, reverse strand). Ensembl gene ENSG00000207769.
Gene Ontology:
Biological process: miRNA-mediated post-transcriptional gene silencing
Cellular component: RISC complex